IL6 (interleukin 6)
Diseases named in the same sentence as IL6 in open-access papers (continued):
Sharing a sentence is not in itself a finding about the gene and the disease.
COVID-19 (continued). "COVID-19 has been associated with an exuberant activation of the host immune system and the excessive production of proinflammatory cytokines, such as IL-1, IL-2, IL-6, IL-10, IL-12, IFN-γ, TNF-α, among others, which may cause tissue injury, particularly on the lungs." (PMID 35090394, 2022). "Lymphocytopenia is negatively correlated with increased serum levels of tumor necrosis factor alpha (TNF-α), IL-6 and IL-10 and postmortem examinations of COVID-19 patients revealed lymphocyte depletion and spleen necrosis in parallel with lymphocyte death." (PMID 35453524, 2022). "This was investigated further using CRP, TNF-α, IL-6, and procalcitonin measurements from plasma samples from hospitalized people with COVID-19 in the ISARIC4C study." (PMID 35531376, 2022). "Among the inflammatory mediators, interleukin-6 (IL-6), interleukin-8 (IL-8), and interleukin-10 (IL-10) are higher in patients with COVID-19-related ARDS." (PMID 35327420, 2022). "Many clinical trials in the context of COVID-19 treatments confirmed this point of view, such as IL-6 blockers, IL-1 receptor antagonists, TNF-α inhibitors, JAK inhibitors, and corticosteroids." (PMID 36111104, 2022). "The TNF-α, IL-6, MIP1b and IL-4 concentrations were higher in the P-COVID-19+ than the P-COVID-19- patients." (PMID 35901034, 2022). "Septic patients had significantly worse microcirculatory flow and higher IL-6 levels than those with COVID-19, while syndecan-1 levels were similar." (PMID 36289881, 2022). "Roactemra® (tocilizumab, an anti-IL6 antibody) has received specific regulatory approval for the treatment of COVID-19 in adults receiving systemic corticosteroid therapy and requiring oxygen supplementation or mechanical ventilation." (PMID 35682871, 2022). "One study from Italy showed that patients with acute COVID-19 had the lowest serum 25(OH)D levels; additionally, they manifested high-circulating IL-6 at admission, which decreased after calcitriol administration." (PMID 35337103, 2022). "Specifically, patients with severe COVID-19 and high body mass indices tend to have increased IL-6 levels, endothelial injury, IFN activation, and cytokine profiles (e.g., IFN-γ, IL15, IL17, MCP1/CCL2, MIP1-beta/CCL4) that suggest macrophage recruitment." (PMID 36289507, 2022). "MMP-7, TGF-β, IL-10, IL-7, TNF-α, and IL-6 were correlated with high lung involvement in COVID-19 patients." (PMID 36286038, 2022). "Similar to other studies, HLA-DR expression on classical monocytes was significantly reduced, which can be mediated by IL-6 overproduction during severe COVID-19." (PMID 35007290, 2022). "This knowledge has spawned initiatives to block IL-6 using receptor inhibitors, including biologics like tocilizumab, which are undergoing trials in moderately to severely ill patients with COVID-19." (PMID 35850685, 2022). "Studies have shown that the level of IL-6 in patients with severe COVID-19 was significantly higher than in patients with mild COVID-19." (PMID 36076167, 2022). "Patients with COVID-19 in general show increased levels of D-dimers, interleukin-6 (IL-6), C-reactive protein (CRP), fibrinogen, and platelets." (PMID 36142094, 2022). "The very early results from three drugs binding to IL-6 and JAKs thus already prove the efficacy of targeting neutrophils and T cells in treating COVID-19." (PMID 35600840, 2022). "For instance, the ratios of IL-2/IL-5, IL-2/IL-10, IL-2/IL-9, IL-6/IL-5, IL-6/IL-10 and IL-6/IL-9 were considerably higher in COVID-19 ICU patients as compared to HC subjects (≈8571-, 4800-, 4444-, 378-, 521-, and 172-fold differences respectively)." (PMID 36363785, 2022). "Among these cytokines, increased interleukin (IL)-18 and IL-6 appear to be the most significant observation, confirming the role of these cytokines in fatal COVID-19." (PMID 35386707, 2022).
COVID-19 (continued). "Biomarkers related to pulmonary fibrosis such as KL-6, SP-D, MMP-7, IL-6 have a great predictive potential in early diagnosis and treatment responsiveness in patients with post-COVID-19 pulmonary fibrosis." (PMID 35371880, 2022). "There was a marked upregulation of CCL2 and IL-6 expression in both severe and moderate COVID-19 groups (P<0.001), with thousands-fold difference compared with controls." (PMID 35982898, 2022). "Analyses of the cytokine concentrations in the sera of these volunteers indicated that COVID-19 patients presented a storm cytokine pattern with high levels of IL-4, IL-6 and IL-8 and low or insignificant levels of IFN-γ, as previously published." (PMID 35440789, 2022). "Circulating levels of IL-6, in particular, have been shown to be significantly higher in severe than mild to moderate disease and to predict COVID-19 severity and survival." (PMID 36140425, 2022). "Eleven studies analyzed the relationship between IL-6 and COVID-19 mortality; these reported OR values from a logistic regression analysis." (PMID 35215138, 2022). "In particular, we showed the activation of human dendritic cells (DC) and monocytes, demonstrating that these cells produced high levels of IL-6 and TNF-α –two hallmark cytokines in COVID-19-associated CRS." (PMID 35392091, 2022). "Antivirals, interferons, corticosteroids, antimalarials, antibiotics, antiparasitics, interleukin-6 inhibitors and cell-based therapy were used for COVID-19 management in the study." (PMID 35566563, 2022). "While IL-6 plasma levels in COVID-19 patients have been widely studied during the pandemic and the results seemed to be consistent, some questions remain unanswered regarding the pattern of the cytokine profile in COVID-19." (PMID 36035415, 2022). "Ocrelizumab (anti-CD20 medication) had a positive effect on MS patients with COVID-19 due to the decreased production of IL-6 by B cells." (PMID 36295089, 2022). "In this meta-analysis, we analyzed serum levels of IL-1β, IL-2, IL-4, IL-6, IL-8, and IL-10 in COVID-19 patients with different disease severities." (PMID 35540724, 2022). "We performed quantitative real-time PCR (qRT-PCR) for representative COVID-19 related host inflammatory cytokine genes and found that a cytokine panel (including IL-6, IL-1β, TNF-α, CCL2, and CXCL9) was induced by SARS-CoV-2 infection." (PMID 34979342, 2022). "The levels of IL-6 and IL-1β are increased in patients with COVID-19, and it has been reported that IL-6 and IL-1β are involved in platelet hyperactivation." (PMID 35907817, 2022). "Second, some patients received steroids or other immunosuppressants for COVID-19 treatment, which would influence serum IL-6 level." (PMID 35242747, 2022). "During the second wave, we studied 170 COVID-19 patients at hospital admission, demonstrating that such patients had lower serum IL-6 levels and less severe inflammation and endothelial damage as compared to patients of the first wave." (PMID 35893398, 2022). "Levels of the proinflammatory cytokine IL-6 were analyzed in COVID-19 blood samples derived from patients with either mild or severe courses of disease." (PMID 35867189, 2022). "Cytokine heatmap revealed that COVID-19 patients presented an overstimulation of these molecules specially IL-6 and monocyte chemoattractant protein-1 (MCP-1) respect to basal state." (PMID 35831294, 2022). "Laboratory findings showed high serum ferritin, CRP and IL-6 levels and D-dimer COVID-19 patients respectively, indicative of severe COVID-19 illness." (PMID 35433146, 2022). "The biopsies of liver and lung injury in deceased COVID-19 patients showed severe inflammatory responses with higher levels of IL-2, IL-6, IL-8." (PMID 35639261, 2022). "Peripheral blood mononuclear cells (PBMCs) from COVID-19 patients released IL-1beta, IL-6, and TNF-alpha ex vivo." (PMID 36009328, 2022). "Levels of IL-6, the cytokine that is most frequently studied in patients with COVID-19, are much lower than in classic ARDS." (PMID 35562935, 2022).
COVID-19 (continued). "Inflammatory indicators such as CRP, procalcitonin, ESR, interleukin-6 (IL-6), and ferritin are seen in COVID-19 patients." (PMID 36299504, 2022). "In patients recovering from mild COVID-19, there was a trend for higher IL-1β, IL-6, and TNF-α production." (PMID 35380990, 2022). "A proteomic study pointed out that LRG1 upregulated in severe COVID-19 patients as a function of IL-6 levels." (PMID 36091008, 2022). "Meanwhile, combining pGSN with IL-6 (AUC=0.904; p=0.003) showed a more significant ability to predict mild COVID-19 and IP-10 (AUC=0.754; p=0.065), HGF (AUC=0.746; p=0.075) and TGF-β1 (AUC=0.765; p=0.078) demonstrated a trend toward significance." (PMID 36148234, 2022). "Particularly in the COVID-19 groups, IL-6 presented a positive correlation with IFN-γ and also IL-12p70 presented a positive correlation with IL-17A." (PMID 35686128, 2022). "A prospective meta-analysis of clinical trials of patients hospitalised for COVID-19 showed that administration of IL-6 antagonists, compared with usual care or placebo, was associated with lower 28-day all-cause mortality." (PMID 35928820, 2022). "The impaired function of T cells and high levels of IL-6 also play a relevant role in the progression of COVID-19 in diabetic patients." (PMID 36406408, 2022). "The serum levels of IL-6 are usually higher in critically ill COVID-19 patients than in severe and moderate patients." (PMID 35822078, 2022). "Late therapeutic interventions with blockers of both PD-1 and IL6 pathways improved clinical outcomes of severe COVID-19 cases and reversed T-cell exhaustion, reducing tissues damage and hyperinflammatory consequences." (PMID 36365007, 2022). "TNFα is an important cytokine involved in immunity and known to act as an amplifier of inflammation while IL6 was identified as the most correlated cytokine to severe and critical COVID-19 conditions." (PMID 35941890, 2022). "IL-6 levels are significantly correlated with worsening oxygen exchange in the lungs of COVID-19 patients and are major predictors of disease progression and mortality." (PMID 35340805, 2022). "Another inflammatory parameter, IL-6, also proves to be a good marker for estimating the severity of COVID-19, as verified in a review and a meta-analytic study." (PMID 35736419, 2022). "In agreement with our findings, previous studies evaluating individual serum samples from COVID-19 patients revealed an enhanced and generalized inflammation, featured by a significant increase in circulating IL-6, IL1RA, CXCL8 levels." (PMID 35720401, 2022). "This is in contrast with current practices in clinical settings, where the administration of an immunotherapeutic agent, such as tocilizumab, to severe COVID-19 patients is guided by measurements only of IL-6 concentrations." (PMID 36678366, 2022). "Elevated concentrations of interleukin-6 have been demonstrated to be an important key factor in COVID-19 host immune impairment." (PMID 35250575, 2022). "Systemic hyper-inflammation with elevated levels of IL-6, sometimes referred to as the “cytokine storm”, is a well-recognised phenomenon of severe COVID-19." (PMID 36474964, 2022). "In most severe patients of COVID-19, improper function of the immune system results in enhanced production of cytokines (cytokine storm) such as IL-2, IL-6, colony-stimulating factor, and TNFs, ultimately leading to death." (PMID 36078094, 2022). "Our group was among the first to provide evidence of metabolic dysregulation in patients with acute COVID-19 as a function of disease severity correlated to circulating levels of inflammatory cytokines such as IL-6." (PMID 36355108, 2022). "This is explained in our study by the significant positive correlation of TNF-α with IL-6 and age in COVID-19 patients." (PMID 36381078, 2022). "A very good example is an observational study regarding IL-6 serum levels as predictors of mortality and response to tocilizumab in COVID-19 patients." (PMID 36289881, 2022).
COVID-19 (continued). "In the present study, we detected significantly higher serum levels of measured cytokines, chemokines, and inflammatory proteins (IP-10, CRP, IFNγ, IL-10, IL-13, IL-17α, IL-23, and IL-6) in COVID-19 patients than in controls." (PMID 36554094, 2022). "About half of the clinical trials being conducted worldwide testing monoclonal antibodies for the management of severe COVID-19 have been performed with IL-6 inhibitors, and in particular with tocilizumab." (PMID 35340805, 2022). "In the present study, we corroborate in a cohort of COVID-19 patients from the southeast of Spain an elevated concentration of the cytokines IL-6, IL-15, IL-18 and IL-1RA." (PMID 35663992, 2022). "In a study, IL-6 in COVID-19 patients emerged superior to other biomarkers like CRP, ferritin, and liver enzymes for predicting death, with an optimal cut-off of 200 pg·L−1, respectively." (PMID 36106257, 2022). "Five studies reporting circulating interleukin-6 (IL-6) levels in male (n = 488) and female (n = 509) COVID-19 patients were included." (PMID 35237162, 2022). "Patients with COVID-19 residing at high-altitude tend to have higher levels of inflammatory cytokines compared to patients living at sea level, particularly IL-6 and TNF-α." (PMID 35090394, 2022). "Within the first group of genes the cytokine Interleukin-6 (IL-6) was identified, one of the clinically validated targets of the anti COVID-19 therapy." (PMID 35614039, 2022). "COVID-19 induces high levels of circulating IL-6, and we found that phospho-STAT3 levels were tightly correlated with plasma IL-6 levels." (PMID 35421120, 2022). "Online in silico tools were applied to evaluate the interaction between the genes in the hsa_circ_0000479/hsa-miR-149-5p/RIG-I, IL-6 axis, and its role in COVID-19-related pathways." (PMID 36081604, 2022). "This study performed in a Mexican population indicates that comorbidities such as: T2DM, hypertension and obesity, as well as elevated levels of glucose, IL-6, LDH and CRP are associated with the COVID-19 severity." (PMID 35464048, 2022). "We analysed inhibition of C-reactive protein (CRP) – a biomarker for IL-6 activity – in patients with COVID-19 or idiopathic multicentric Castleman disease (iMCD) treated with tocilizumab (anti-IL-6R) or siltuximab (anti-IL-6), respectively." (PMID 35928820, 2022). "Local or systemic cytokine release is typical with COVID-19 and interleukin (IL)-6, IL-1β, and tumor necrosis factor-α (TNF-α) play key roles in the progression and exacerbation pathogenesis of COVID-19." (PMID 36590587, 2022). "In COVID-19 patients, IL-6 and TNFα are among the most important ones, given that their levels are strong independent predictors of patient survival." (PMID 35563218, 2022). "Recent studies have shown that interleukin 6 (IL-6) is a strong independent predictor of mortality in patients with COVID-19." (PMID 35371397, 2022). "In conclusion, in addition to illness severity and PaO2/FIO2 ratio, VR, D-Dimer and IL-6 were independent predictors of mortality in COVID-19 ARDS." (PMID 35308552, 2022). "Studies have shown that rising levels of IL-6 are correlated with disease severity and are particularly useful in identifying individuals who have progressed to more severe stages of COVID-19." (PMID 36381779, 2022). "Among the cytokines analyzed, those that correlated with a worse prognosis of COVID-19 were resistin, IL-6, IL-8, IL-15, MCP-1 and TNF-α." (PMID 35330391, 2022). "IL-6 inhibitors are widely available for use in the treatment of COVID-19 as monoclonal antibodies targeting IL-6 (siltuximab) or IL-6R (tocilizumab and sarilumab)." (PMID 36115998, 2022). "The level of IL-6 was significantly higher in COVID-19 patients than healthy individuals (7.63 ± 6.30 vs. 5.54 ± 2.10, P=0.006)." (PMID 36381078, 2022). "During the hyperinflammation phase of COVID-19, IL-6 is frequently the most highly elevated cytokine in the plasma." (PMID 35746559, 2022).
COVID-19 (continued). "Both the mean blood concentration of vitamin D and the levels of IL-6 were revealed to be independent predictors of COVID-19 severity and death." (PMID 36295519, 2022). "Symptomatic COVID-19 patients had significantly (p < 0.05) higher levels of IL-10, IL-2, IL-2R, IL-6, IL-8 GM-CSF IP-10, TNF-α, IL-4, IL-5, IL-12, IFN-γ and MIP-1β compared to the asymptomatic cases." (PMID 36184636, 2022). "The authors concluded that baseline IL-6 greater than 30 pg/mL predicts IMV requirements in patients with COVID-19 and contributes to establishing an adequate indication for tocilizumab administration." (PMID 36289881, 2022). "More specifically, severe outcomes of COVID-19 are the result of several pro-inflammatory cytokines, including IL-6, whose increased levels contribute to the cytokine storm." (PMID 36532776, 2022). "IL-6 was the most potent predictor for severe COVID-19, since the AUC value was >0.800 at a cut-off value 51.0 pg/mL with 100% sensitivity and 68% specificity." (PMID 36675695, 2022). "Our results indicated that serum levels of IL-2, IL-4, IL-6, and IL-10 were increased in COVID-19 patients compared to healthy subjects." (PMID 35540724, 2022). "Similar to high IL-6 and IL-10 activity found in COVID-19 patients, elevated IL-10 plays a key role in the development of pulmonary injury and fibrosis." (PMID 36119044, 2022). "Whereas IL-6 was good predictor of COVID-19 in severe cases (AUC > 0.800), IL-18 and IL-35 were fair." (PMID 36675695, 2022). "To clarify the co-action of IL-6 in patients with COVID-19 and NAFLD, we extensively searched relevant literature." (PMID 36380355, 2022). "Clazakizumab also targets IL-6 and is currently being evaluated for safety in several clinical trials of patients with life-threatening COVID-19." (PMID 35720378, 2022). "This likely plays a role in the multisystemic dysfunction that can occur in patients with severe COVID-19 and is characterized by very high levels of C-reactive protein, interleukin-6, and ferritin." (PMID 36497138, 2022). "In our previous study, we have found that COVID-19 patients infected with P. aeruginosa express higher levels of IL-6, CRP and PCT." (PMID 35139898, 2022). "Particular attention must be paid to the inhibition of factors such as IL6, GCSF, GMCSF, and TNFα that are associated with highly severe disease and ICU admission of COVID-19 patients." (PMID 36140223, 2022). "Interleukin-6 (IL-6) is a biomarker of inflammation, the advanced stage of COVID-19, and several cancers, including ovarian cancer." (PMID 35735559, 2022). "Pro-inflammatory signatures of severely affected COVID-19 patients feature elevations of interleukin-1β (IL-1β), IL-6, and tumor necrosis factor alpha (TNF-α)." (PMID 35600840, 2022). "In fact, patients with COVID-19 display a pro-inflammatory (IL-1β, IL-6, IL-7, IL-8, IL-9, FGF, G-CSF, GM-CSF, IFN-ɣ, CXCL10, CCL2, CCL3, CCL4, PDGF, TNFα, and VEGF) and regulatory cytokine profile (IL-10 and TGFβ; cytokine storm)." (PMID 33995342, 2021). "IL-6 can exhibit both proinflammatory and anti-inflammatory properties, but an increase in its level in COVID-19 primarily plays a proinflammatory role, since it is an active participant in the so-called “cytokine storm”." (PMID 34956420, 2021). "We observed that IL-6 levels were elevated shortly after symptom onset in patients who eventually developed severe/critical COVID-19." (PMID 34938289, 2021). "Tocilizumab and CPT treatments, the two important therapy methods for COVID-19, decreased the level of IL-6 and relieved inflammation." (PMID 33746945, 2021). "In our study, we found that most of the cytokines recovered in the convalescent individuals except that a significantly higher proportion of COVID-19 convalescent individuals presented with elevated IL-5, IL-6, and IL-1β levels." (PMID 34234102, 2021).